PTAFR (platelet activating factor receptor)
Description:
Receptor for platelet activating factor, a chemotactic phospholipid mediator that possesses potent inflammatory, smooth-muscle contractile and hypotensive activity. Seems to mediate its action via a G protein that activates a phosphatidylinositol-calcium second messenger system.
Synonyms: PAFr
Tractability: Small molecule: an approved drug acts on it; a structure with a bound ligand is known; a high-quality ligand is known; it belongs to a druggable protein family. Antibody: UniProt places it where antibodies can reach, with high confidence; its Gene Ontology location is reachable by antibodies, with high confidence; UniProt predicts a signal peptide or a membrane-spanning region. PROTAC: its protein half-life has been measured; a small molecule that binds it is known.
Target class: PAF receptor; Membrane receptor; Small molecule receptor (family A GPCR); Lipid-like ligand receptor (family A GPCR); Family A G protein-coupled receptor
Chemical probes: APAFANT (high quality), BEPAFANT (high quality), S-Bepafant (high quality)
Safety:
Unwanted effects reported when the protein is acted on. In parentheses: how it was acted on, where the effect was seen, and who reports it.
bronchoconstriction (activation, acute dosing; respiratory, renal, immune, cardiovascular, blood; source: Lynch et al. (2017))
decreased blood pressure (activation, acute dosing; respiratory, renal, immune, cardiovascular, blood; source: Lynch et al. (2017))
decreased cardiac contractility (activation, acute dosing; respiratory, renal, immune, cardiovascular, blood; source: Lynch et al. (2017))
decreased heart rate (activation, acute dosing; respiratory, renal, immune, cardiovascular, blood; source: Lynch et al. (2017))
decreased inflammation (inhibition, acute dosing; respiratory, renal, immune, cardiovascular, blood; source: Lynch et al. (2017))
decreased pain (inhibition, acute dosing; respiratory, renal, immune, cardiovascular, blood; source: Lynch et al. (2017))
decreased urinary sodium excretion (activation, acute dosing; respiratory, renal, immune, cardiovascular, blood; source: Lynch et al. (2017))
decreased urine excretion (activation, acute dosing; respiratory, renal, immune, cardiovascular, blood; source: Lynch et al. (2017))
increased airway responsiveness to antigens (activation, acute dosing; respiratory, renal, immune, cardiovascular, blood; source: Lynch et al. (2017))
inflammation (activation, acute dosing; respiratory, renal, immune, cardiovascular, blood; source: Lynch et al. (2017))
pain (activation, acute dosing; respiratory, renal, immune, cardiovascular, blood; source: Lynch et al. (2017))
platelet aggregation (activation, acute dosing; respiratory, renal, immune, cardiovascular, blood; source: Lynch et al. (2017))
Gene: Protein-coding gene on chromosome 1 (28,147,166 to 28,194,083, reverse strand). Ensembl gene ENSG00000169403.
Subcellular location: Cell membrane
Subcellular location (Human Protein Atlas): Plasma membrane; Nucleoplasm; Vesicles
Pathways (Reactome):
Immune System: Interferon gamma signaling; Interleukin-10 signaling; Neutrophil degranulation
Signal Transduction: Class A/1 (Rhodopsin-like receptors); G alpha (q) signalling events
Gene Ontology:
Molecular function: phospholipid binding; platelet activating factor receptor activity; protein binding; G protein-coupled purinergic nucleotide receptor activity; G protein-coupled receptor activity; lipopolysaccharide binding; lipopolysaccharide immune receptor activity
Biological process: phospholipase C-activating G protein-coupled receptor signaling pathway; chemotaxis; G protein-coupled receptor signaling pathway; immune response; inflammatory response; G protein-coupled purinergic nucleotide receptor signaling pathway; lipopolysaccharide-mediated signaling pathway
Cellular component: plasma membrane; membrane; secretory granule membrane; tertiary granule membrane
Genetic constraint (gnomAD): Loss-of-function variants: 10 observed, 18.74 expected, observed/expected ratio (o/e) 0.53, 90% interval 0.33 to 0.9. The upper end of that interval is the gene's LOEUF score, 0.9, which puts it in group 3 of 6, group 1 being the genes least tolerant of losing a copy. Missense variants: 337 observed, 474.4 expected, observed/expected ratio (o/e) 0.71, 90% interval 0.65 to 0.78. Synonymous variants: 156 observed, 186.75 expected, observed/expected ratio (o/e) 0.84, 90% interval 0.73 to 0.95.
Homologues: Orthologues: chimpanzee PTAFR (99% identical), macaque PTAFR (97% identical), rabbit PTAFR (86% identical), dog PTAFR (84% identical), pig PTAFR (83% identical), guinea pig PTAFR (83% identical), mouse Ptafr (82% identical), rat Ptafr (79% identical), tropical clawed frog ptafr (59% identical), zebrafish ptafr (45% identical). Paralogues in human: P2RY12 (26% identical), GPR34 (24% identical), GPR87 (23% identical), P2RY14 (23% identical), P2RY13 (22% identical), GPR171 (22% identical).
Diseases named in the same sentence as PTAFR in open-access papers:
PTAFR is named in the same sentence as 69 diseases in open-access papers, as found by Europe PMC text mining. Sharing a sentence is not in itself a finding about the gene and the disease. The quoted sentences say what the papers report.
melanoma (9 papers, 2012 to 2022). A malignant, usually aggressive tumor composed of atypical, neoplastic melanocytes. "Moreover, the expression of platelet-activating factor receptor (PAF-R) is linked to a higher metastatic potential in melanoma cells." (PMID 31003534, 2019). "The crosstalk between protease-activated receptor 1 and platelet-activating factor receptor has been demonstrated to regulate the expression of melanoma cell adhesion molecule (MCAM/MUC18) metastasis of melanoma." (PMID 36185647, 2022). "Melanoma cells often express receptors for multiple growth factors and cytokines, which regulate their growth, including platelet-activating factor-receptor (PAF-R), a G-protein coupled receptor expressed in various types of cell." (PMID 25695262, 2015). "Melanoma cells express the platelet-activating factor receptor (PAFR) and, thus, respond to PAF, a bioactive lipid produced by both tumour cells and those in the tumour microenvironment such as macrophages." (PMID 22570511, 2012). "Given our reports that an activation of platelet-activating factor-receptor (PAF-R) augments the growth and impede efficacies of therapeutic agents in experimental melanoma, we also sought to determine if PAF-R mediates anti-melanoma activity of ASA." (PMID 28636992, 2017). "PTAFR (platelet-activating factor receptor) expression was decreased after UVR, although activation of this receptor on melanoma cells has been demonstrated to enhance their proliferation, invasiveness, and metastatic capabilities." (PMID 22745913, 2012).
ovarian carcinoma (5 papers, 2014 to 2022). A malignant neoplasm originating from the surface ovarian epithelium. "We previously identified platelet-activating factor receptor (PAFR) as being overexpressed in ovarian cancer and found that its ligand PAF evoked EGFR phosphorylation using the phospho-antibody microarray." (PMID 25261977, 2014). "PTAFR has been shown to activate the EGFR and ERK signaling pathways in ovarian cancer cells, therefore potentially contributing to cancer progression." (PMID 35625966, 2022). "Therefore, targeting PTAFR could be a potential approach for the treatment of ovarian cancer." (PMID 35625966, 2022). "Patients and in vitro generated data indicate that PAF/PTAFR and PLA2G7/PAF-AH signaling plays a crucial role in BRCA1 mutant ovarian cancer." (PMID 34206491, 2021).
COVID-19 (4 papers, 2020 to 2023). A disease caused by infection with severe acute respiratory syndrome coronavirus 2. "Surprisingly, GCs therapy elevated PAF-receptor (PTAFR) gene expression relative to untreated COVID-19 patients, which may be associated with pro-inflammatory effects." (PMID 36851787, 2023).
bacteremia (3 papers, 2011 to 2021). "In this study, we report that the receptor for this important human pathogen on airway epithelial cells is the platelet activating factor receptor (PAFr), an immunomodulatory molecule shown by others to play a role in promoting bacterial sepsis." (PMID 23696740, 2013).
cervical cancer (3 papers, 2018 to 2023). A primary or metastatic malignant neoplasm involving the cervix. "PTAFR is high expressed in cervical cancer samples when compared with normal cervical tissue, which protect tumor cells from radiation-induced cell death." (PMID 37101794, 2023). "Our results show that PTAFR expression was upregulated in cervical cancer clinical samples when compared to normal cervical tissue." (PMID 29459885, 2018). "Cervical cancer samples presented higher levels of PAF-receptor gene (PTAFR) when compared with normal cervical tissue." (PMID 29459885, 2018). "We first analyzed PAFR (PTAFR) expression in two cervical cancer datasets retrieved from GEO web database." (PMID 29459885, 2018). "In cervical cancer patients submitted to radiotherapy (RT), the expression of PTAFR was significantly increased." (PMID 29459885, 2018).
dengue (3 papers, 2018 to 2024). "We considered that rupatadine, a platelet-activating factor receptor inhibitor, might modulate dengue-associated vascular leak." (PMID 29497121, 2018). "Having higher levels of ALOX-12 and PTAFR expression and lower levels of CCL6/MRP-1, CCL8/MRP-2, CCL12/MCP-5, and IL1R1 expression helps fight dengue." (PMID 38919218, 2024).
lung carcinoma (3 papers, 2020 to 2023). "Herein we find that SP attaches to lung cancer cells via binding pneumococcal surface protein C (PspC) to platelet-activating factor receptor (PAFR)." (PMID 36685035, 2023).
myocardial infarction (3 papers, 2019 to 2022). Gross necrosis of the myocardium, as a result of interruption of the blood supply to the area, as in coronary thrombosis. "Overexpression of Let-7d (5p) attenuated collagen deposit, impeded cardiac fibrosis, and improved cardiac function in myocardial infarction mice via regulating the platelet-activating factor receptor (Ptafr)." (PMID 30934671, 2019). "Moreover, PTAFR down-regulation is also correlated with the proliferation of cardiac fibroblasts and the deposition of collagen, which finally inhibits fibrous fibers after myocardial infarction in cardiac fibroblasts treated with angiotensin II." (PMID 35572136, 2022).
pancreatic cancer (3 papers, 2011 to 2021). "In turn, the most commonly deleted gene was MYOCD, a cancer related gene which also displayed LOH in most of our cases (80%); other frequently deleted cancer-associated genes included the EYA3, NR2C1, PTAFR, and the DCC cancer associated genes which have also been involved in pancreatic cancer." (PMID 21811587, 2011). "WEB2086, a platelet-activating factor receptor (PAFR) antagonist, was shown to reduce gemcitabine-induced exosome release in PAFR-positive pancreatic cancer cells." (PMID 33477340, 2021).
pneumonia (3 papers, 2017 to 2021). An acute, acute and chronic, or chronic inflammation focally or diffusely affecting the lung parenchyma, caused by an infection in one or both of the lungs (by bacteria, viruses, fungi, or mycoplasma.). "Findings on the potential role of TBXA2R and PTAFR in the increased risk of antipsychotic-associated pneumonia derived from CT-link were further investigated using Cytoscape." (PMID 29077727, 2017). "Two targets, thromboxane A2 receptor (TBXA2R) and plateletactivating factor receptor (PTAFR) were found to be novel AP target receptorspotentially associated with pneumonia." (PMID 29077727, 2017). "The identified AP off-targets, TBXA2R and PTAFR, in black, are linked, either directly or indirectly, to a group of nodes, shown in blue, which likely contribute to the increased risk of developing pneumonia-related symptoms after activation of TBXA2Ror PTAFR." (PMID 29077727, 2017). "Findings from this study confirmed existing receptor targets for AP drugs but also provided two novel off-targets that may lead to AP-associated pneumonia, namely PTAFR and TBXA2R." (PMID 29077727, 2017). "In fact, periodontopathic bacteria enhance the expression of influenza virus receptor and platelet-activating factor receptor, which are the receptors for etiological bacteria of pneumonia such as Streptococcus pneumoniae and Pseudomonas aeruginosa." (PMID 33572938, 2021). "Prevotella intermedia, one of the periodontal pathogens, has been determined to increase the expression of the platelet-activating factor receptor (PAFR) on the alveolar epithelial cells, a receptor for pneumonia-causing bacteria." (PMID 34207046, 2021). "The novel mechanisms concerning TBXA2R and PTAFR as potential mediators of pneumonia symptoms constitute an important finding of this study." (PMID 29077727, 2017). "Among the off-targets identified, further analysis was carried out for the two potentially novel proteins involved in AP-associated pneumonia, TBXA2R and PTAFR." (PMID 29077727, 2017). "Biological pathways constructed using Cytoscape identified plausible biological links potentially leading to pneumonia downstream of TBXA2R and PTAFR." (PMID 29077727, 2017).
asthma (2 papers, 2024 to 2025). "PTAFR, a membrane protein, specifically binds to platelet‐activating factor (PAF) and mediates various BPs, including immune responses, inflammation, platelet aggregation and vascular regulation, thereby contributing to the progression of diseases such as asthma, cardiovascular disorders and cancer." (PMID 41498029, 2025).
atherosclerosis (2 papers, 2015 to 2016). A disease characterized by the build-up of fatty material and calcium deposition in the arterial wall resulting in partial or complete occlusion of the arterial lumen. "An earlier study demonstrated that lysoPC increases Ca2+i via stimulating platelet-activating factor receptor in mouse macrophages, which correlates to the pathogenesis of atherosclerosis." (PMID 27472391, 2016). "OxLDL can promote atherosclerosis development by inducing the recruitment of platelet-activating factor receptor and CD36 in detergent resistant membranes." (PMID 26628893, 2015).
breast carcinoma (2 papers, 2021 to 2022). "The expression of PTAFR in breast cancer cells and osteoclasts increases significantly, while, upon PTAFR downregulation, the breast cancer cell migration and osteoclast production reduce in the bone metastasis models." (PMID 35572136, 2022).
chronic obstructive pulmonary disease (2 papers, 2016 to 2025). A chronic and progressive lung disorder characterized by the loss of elasticity of the bronchial tree and the air sacs, destruction of the air sacs wall, thickening of the bronchial wall, and mucous accumulation in the bronchial tree. "Expression of the platelet-activating factor receptor is upregulated in the respiratory epithelium of smokers and chronic obstructive pulmonary disease patients." (PMID 27782846, 2016).
colitis (2 papers, 2021 to 2022). Inflammation of the colon. "Also, platelet activating factor receptor regulates lung inflammation caused by colitis by NLRP3 inflammation." (PMID 34409047, 2021).
ischemia (2 papers, 2021). A hypoperfusion of the BLOOD through an organ or tissue caused by a PATHOLOGIC CONSTRICTION or obstruction of its BLOOD VESSELS, or an absence of BLOOD CIRCULATION. "Furthermore, neuronal EV as an endogenous protective factor inhibits microglial phagocytosis by targeting platelet-activating factor receptor, thereby reducing ischemia-induced neuronal death." (PMID 34912217, 2021). "Furthermore, miR-98 derived from Ne-Exos acts as a post-ischemic endogenous protective factor by inhibiting microglial phagocytosis via the targeting of platelet-activating factor receptor (PAFR), thereby attenuating ischemia-induced neuronal death." (PMID 34070696, 2021).
pneumococcal infection (2 papers, 2017 to 2022). Infections with bacteria of the species streptococcus pneumoniae. "We sought to assess whether oxidative stress plays a role in susceptibility to pneumococcal infection via the platelet activating factor receptor." (PMID 28278175, 2017). "Traffic-related PM10 increases pneumococcal infection via increasing the expression of platelet-activating factor receptor (PAFR), a receptor co-opted by pneumococci to adhere to cells." (PMID 35598440, 2022).
renal fibrosis (2 papers, 2022). A final common manifestation of a wide variety of chronic kidney diseases characterized by glomerulosclerosis and tubulointerstitial fibrosis. "And it was shown that PTAFR is one of the central genes of 18β-glycyrrhetinic acid to alleviate renal fibrosis by inhibiting the inflammatory response." (PMID 36534664, 2022). "Additionally, in the renal fibrosis model induced by heavy ethanol intake, the expression of the inflammatory factor, TGFβ, and closely related indicators of renal fibrosis decrease significantly in the PTAFR knockout mice; finally, the renal fibrosis is inhibited." (PMID 35572136, 2022).
schizophrenia (2 papers, 2012 to 2020). A major psychotic disorder characterized by abnormalities in the perception or expression of reality. "Besides categories related to hematological function, the Tan schizophrenia module was also enriched for the Neurological Disease category (CCL5, PRKCQ, PTAFR, AKR1B1, CD247, IL10RA and KHSRP)." (PMID 22761806, 2012).
bone metabolic disorders (1 paper, 2025). "In contrast, PTAFR deficiency or the use of PTAFR antagonists significantly reduces bone loss in ovariectomised mice, suggesting that PTAFR acts as a bridge connecting inflammation and bone metabolic disorders." (PMID 41498029, 2025).
cervical tumors (1 paper, 2018). "In the second series (GSE3578), we found that the mRNA level of PTAFR was increased in cervical tumors (n = 26) after the patients underwent RT treatment protocol." (PMID 29459885, 2018). "Also, PTAFR mRNA level was increased in cervical tumors after RT treatment." (PMID 29459885, 2018).
chronic lung disease (1 paper, 2019). According to the definitions of the American and British Thoracic Societies, including pulmonary functional tests, X-rays, and CT scans for items such as fibrosis, bronchiectasis, bullae, emphysema, nodular or lymphomatous abnormalities. "In patients with chronic lung diseases, receptors for pneumococci, such as platelet-activating factor receptor, are overexpressed in the respiratory tract, increasing the risk of chronic colonization and invasive infections." (PMID 30699137, 2019).
colon cancer (1 paper, 2021). "A PTAFR antagonist reduced inflammation-induced colon carcinogenesis in rats, and β-catenin was localized in the cell membrane in healthy tissue, while it was overexpressed in the nucleus in precursor lesions and colon cancer." (PMID 34206491, 2021).
diabetes (1 paper, 2024). "The mRNA expression of platelet activating factor receptor (PAFR) was significantly higher in patients with diabetes, which might cause macrovascular disease through impaired endothelial function." (PMID 38166912, 2024).
hepatocellular carcinoma (1 paper, 2023). A malignant tumor that arises from hepatocytes. "Activation of the platelet-activating factor (PAF)/PTAFR pathways has also been suggested to cause hepatocellular carcinoma cell migration and invasion." (PMID 37838792, 2023).
house dust mite allergy (1 paper, 2021). "Furthermore, the fatty acid translocase CD36 is 20-fold stronger expressed in CD11b+CD11c+ MDSCs than in CD11b+CD11c− MDSCs and serves in association with the platelet-activating factor receptor as an important mediator of Th2-mediated house dust mite allergy development." (PMID 34721430, 2021).
invasive carcinoma (1 paper, 2018). A carcinoma that is not confined to the epithelium, and has spread to the surrounding stroma. "We observed that PTAFR expression was upregulated in invasive carcinomas (n = 33) when compared with age-matched normal cervical tissues from hysterectomy specimens (n = 19) (GSE9750)." (PMID 29459885, 2018).